XAF1 (XIAP associated factor 1)
Diseases named in the same sentence as XAF1 in open-access papers (continued):
Sharing a sentence is not in itself a finding about the gene and the disease.
gastric cancer (13 papers, 2007 to 2026). A primary or metastatic malignant neoplasm involving the stomach. "Over‐expression of XAF1F, one of XAF1 transcript variants, in gastric cancer‐derived circulating tumour cells with EMT characteristics is shown to promote tumour invasion, lymph node metastasis and venous invasion." (PMID 35810383, 2022). "The significant correlation of XAF1 methylation with many clinico-pathological parameters suggested that it may associate with the prognosis of gastric cancer patients." (PMID 23826230, 2013). "Circulating methylated XAF1 DNA was associated with tumor burden and malignant progression, which may be a valuable biomarker for diagnosis of gastric cancer, predicting patients’ prognosis and monitoring tumor recurrence after surgery treatment." (PMID 23826230, 2013). "Restoration of XAF1 expression significantly increased apoptosis level in gastric cancer cell lines and improved the sensitivity of gastric cancer cells to 5-fluorouracil and cisplatin-induced apoptosis." (PMID 33747900, 2021). "The primer pair used flanks three CpGs in the region -196 to -235, which overlaps with a region already found to be responsible for XAF1 silencing in gastric cancer." (PMID 28122345, 2017). "Conversely, downregulation of the ubiquitously expressed XAF1, a negative regulator of XIAP, is described in several cancer lines, and promoter methylation has been shown to cause XAF1 silencing in some gastric cancers." (PMID 25636036, 2015). "In the present study, we examined XAF1 promoter methylation in paired tissue and serum samples from a large panel of patients with gastric cancer, and evaluated circulating methylated XAF1 as a potential biomarker for gastric cancer." (PMID 23826230, 2013). "In human gastric cancer, XAF1 has been reported to be frequently and significantly down-regulated and this down-regulation of XAF1 probably through DNA hypermethylation of specific CpG sites." (PMID 23826230, 2013). "Of note, the methylated status of XAF1 significantly correlated with some clinico-pathological parameters in gastric cancer, such as lymph node metastasis, T-stage, H. pylori infection, etc (all p<0.05)." (PMID 23826230, 2013). "Dysfunction of XAF1 is frequent and is regulated through XAF1 promoter hypermethylation in gastric cancer." (PMID 23826230, 2013). "XAF1 mRNA expression was reactivated in both gastric cancer cell lines, accompanied by demethylation of XAF1 promoter, indicating that XAF1 is transcriptionally silenced in these cells by DNA hypermethylation." (PMID 23826230, 2013). "To check XAF1 protein level in gastric cancer tissues, we performed immunohistochemical analysis in the 202 gastric cancer tissues and their corresponding PCHNTs." (PMID 23826230, 2013). "First we demonstrated a great consistency in detecting XAF1 methylation between sera and primary gastric cancer tissues." (PMID 23826230, 2013). "The XAF1 expression was significantly reduced in gastric cancer samples as compared with that in normal controls and PCHNTs (p<0.001)." (PMID 23826230, 2013). "Until the due date of Follow-up, 113 of 168 patients with XAF1 hypermethylation in gastric cancer tissues went rapid disease progression or died." (PMID 23826230, 2013). "To explore the molecular mechanisms responsible for the XAF1 silence, we examined XAF1 promoter methylation in a large panel gastric cancer tissues (n = 202) and normal controls (n = 88) using a real-time MSP technology." (PMID 23826230, 2013). "Clinico-pathological correlations of XAF1 promotor hypermethylation in gastric cancer tissues and in sera." (PMID 23826230, 2013). "The average XAF1 protein level in 20 gastric cancer tissues was significantly lower than that in PCHNTs (p<0.05)." (PMID 23826230, 2013). "The DNA hypermethylation of XAF1 significant correlated with the down-regulation of XAF1 in both mRNA and protein levels in gastric cancer tissues." (PMID 23826230, 2013).
gastric cancer (continued). "The feasibility of this concept has recently been proven in an immunohistochemical investigation on the prognostic effect of XIAP and XAF1 in gastric cancer." (PMID 19664236, 2009). "In gastric cancers, the relative decrease in xaf1 transcript level correlates with the stage and grade of the tumor, suggesting that loss of XAF1 contributes to the process of tumorigenesis." (PMID 17376236, 2007). "This is in accordance with one previous study, showing that XAF1 could inhibit AKT signaling in gastric cancer cells." (PMID 33734579, 2021). "Furthermore, it has been demonstrated that adenovirus vector-mediated XIAP-associated factor 1 (XAF1) expression induces autophagy and autophagic cell death via Beclin-1 upregulation in gastric cancer cells." (PMID 32019552, 2020). "XAF1 methylation was detected in 141 (69.8%) serum DNAs from the 202 gastric cancer patients." (PMID 23826230, 2013). "In addition, 5-Aza-CdR treatment significantly restored XAF1 expression in XAF1 silenced gastric cancer cell lines." (PMID 23826230, 2013). "Clinico-pathological correlations of XAF1 protein expression in gastric cancer tissues." (PMID 23826230, 2013). "On the basis of these observations, especially we detected a high frequency of XAF1 DNA methylation in gastric cancer tissues (83.2%), we decided to explore the possibility to use XAF1 promoter methylation in the serum as a biomarker in gastric cancer patients." (PMID 23826230, 2013). "We detected high frequency of XAF1 methylation in primary gastric cancer (83.2%), suggesting that it may be a good biomarker if XAF1 methylation could be detectable in serum." (PMID 23826230, 2013). "We detected a high frequency (83.2%) of DNA hypermethylation of XAF1 in gastric cancer tissues." (PMID 23826230, 2013). "In addition, TNM stages and age at diagnosis could be considered as the influencing factor of prognosis in gastric cancer, only when the effect of XAF1 methylation was eliminated." (PMID 23826230, 2013). "Similarly, Kaplan-Meier analysis proved that patients with positive serum XAF1 methylation had significantly lower DFS than that in the patients without serum XAF1 methylation (p<0.0001), indicating that XAF1 promoter methylation in serum was an unfavorable predictor for the gastric cancer patients." (PMID 23826230, 2013). "XAF1 has been shown to be frequently down-regulated in human gastric cancer (GC)." (PMID 23826230, 2013). "To investigate the molecular mechanisms for the XAF1 silence in gastric cancers, we applied a real-time MSP technology to study the DNA methylation status of XAF1 promoter." (PMID 23826230, 2013). "To investigate XAF1 gene expression profile, we examined mRNA expression of XAF1 in 88 non-cancer volunteers, and 202 primary gastric cancer tissues and their corresponding PCHNTs." (PMID 23826230, 2013). "In contrast, in the 34 patients without XAF1 hypermethylation in their gastric cancer tissues, only 5 patients were deteriorating, and the Median DFS was 39.6 months." (PMID 23826230, 2013). "The frequency of XAF1 hypermethylation in gastric cancer tissues, corresponding PCHNTs and non-cancer controls were 83.2% (168/202), 24.8% (50/202) and 5.7% (5/88), respectively." (PMID 23826230, 2013). "And in the 34 gastric cancer patients without XAF1 methylation in their gastric cancer tissues, no methylation was found in all the serum DNAs." (PMID 23826230, 2013). "Kaplan-Meier analysis demonstrated that patients with XAF1 hypermethylation in their gastric cancer tissues exhibited an obvious worse survival than that without XAF1 hypermethylation (p<0.0001)." (PMID 23826230, 2013). "However, high expression of XAF1 protein was only detected in 16.8% (34/202) of gastric cancer tissues; majority of gastric cancer tissues were absent or at a low level of XAF1 protein." (PMID 23826230, 2013).
gastric cancer (continued). "In addition, like XAF1 methylation status in gastric cancer tissues and the sera significantly correlated with lymph node metastasis, T-stage, clinical stage, and other clinico-pathological parameters (all p<0.05)." (PMID 23826230, 2013). "Interestingly, treatment of gastric cancer cells with TSA, a histone deacetylase inhibitor also restored XAF1 expression, alone or combined with 5-Aza-CdR treatment, indicating that histone modification may also be involved in XAF1 regulation." (PMID 23826230, 2013). "Therefore, our data suggest that detection of XAF1 methylation in circulating DNA could be used as a non-invasive biomarker for diagnosis of gastric cancer." (PMID 23826230, 2013).
viral infection (13 papers, 2016 to 2025). "We sought to explore the underlying molecular mechanism for the protective role of XAF1 during viral infection." (PMID 35972291, 2022). "Moreover, XAF1 is a sensitive and reliable gene that positively correlates with the viral infection, suggesting that XAF1 is a potential diagnostic marker for viral infectious diseases." (PMID 35972291, 2022). "In line with this, in H1N1/WSN and H5N3 virus infection an elevated level of IFIT1 was associated with increased expression of anti-apoptotic genes XIAP associated factor 1 (XAF1) in both viruses and TNF receptor-associated factor 1 (TRAF1) in H5N3 virus infection in response to early cell death." (PMID 28558796, 2017). "To explore the signaling pathways that control the induction of XAF1 during viral infection, we transfected PMs with two viral RNA mimics, poly(I:C) and 3p-hpRNA, which potently activate the RIG-I-MAVS-TBK1-IRF3-IFN-I signaling axis." (PMID 35972291, 2022). "Given the rapid turnover of IRF1 mRNA and IRF1 proteins, XAF1 has more potential than IRF1 to be a sensitive and reliable diagnostic marker of viral infectious diseases." (PMID 35972291, 2022). "Taken together, these results demonstrated that upregulation of XAF1 expression during viral infection broadly protected the host against RNA viruses." (PMID 35972291, 2022). "Despite the potential correlation between XAF1 and viral infection, the function of XAF1 in the hosts fight against viral infection is unclear." (PMID 35972291, 2022). "This gene set includes interferon-induced genes that encode antiviral proteins (OAS proteins), chemokine families (CXCL), interferon Induced proteins with tetratricopeptide repeats (IFITs) known to confer immunity against viral infections and transcription factors (XAF1, ETV7)." (PMID 41327031, 2025). "Therefore, we speculated that induction of the transcription factor IRF1 determined the elevated XAF1 expression during viral infection." (PMID 35972291, 2022). "In the context of dual influences from immunosuppression and viral infection, KTRs exhibited more specific plasma cells, along with significant enrichment of dysfunctional GZMB and XAF1 double-positive effector T cells and IFI27-positive monocytes." (PMID 38238762, 2024). "Therefore, further research on XAF1 may lead to a new link between cancer and viral infection." (PMID 36834974, 2023). "IRF1 transcriptionally induced by the phosphorylated STAT1 and stabilized by XAF1 further facilitates the induction of the IRF1 target genes such as DDX58, DDX60, MX1, and OAS2 during viral infection." (PMID 35972291, 2022). "To investigate how XAF1 facilitates the induction of IRF1 target genes, we first measured the IRF1 expression during viral infection." (PMID 35972291, 2022). "In our analysis, we have observed that XAF1 and IFI44 protein in virus-infected cells, which could be targeted against viral infection." (PMID 32566414, 2020). "In addition to the important roles of XAF1 as a proapoptotic factor in cancer, it is unknown whether XAF1 is also involved in the regulation of IFN-I-triggered antiviral immunity, as multiple antiviral ISGs do during viral infection." (PMID 35972291, 2022). "Additional powerful biomarkers were identified for Pacific (Trim21, IFI) and Atlantic (CD9, RAD1, SACS, XAF1) salmon whereby assays did not work across species; if re-designed, these biomarkers may also contribute to the universal separation of viral disease states across species." (PMID 28702195, 2017). "In particular, 8 genes (Mx1, EPSTI1, XAF1, IFI44L, GBP1, SAMD9, SAMD9L, and CMPK2) were expressed in the highly resistant cell lines HPAF-II and Hs766T but not the highly permissive cell lines MIA PaCa-2 and Capan-1 in the absence of virus infection." (PMID 27533247, 2016).
glioblastoma (8 papers, 2007 to 2024). The most malignant astrocytic tumor (WHO grade IV). "The loss of XAF1 in three different shRNA stable glioblastoma cell lines completely abolished the sensitization effect of IFN-β observed in the parental SF539." (PMID 17376236, 2007). "We used the conventional bisulfite DNA modification and sequencing method to determine the methylation status in the CpG sites of xaf1 promoter in glioblastoma (SF539, SF295), neuroblastoma (SK-N-AS) and cervical carcinoma (HeLa) cells." (PMID 17376236, 2007). "To further understand the importance of xaf1 gene induction in IFN-β-sensitization to TRAIL-mediated cell death, we established stable glioblastoma SF539 cell lines carrying specific xaf1 shRNA." (PMID 17376236, 2007). "Functional knockdown of xaf1 through shRNA is sufficient to eliminate the IFN-β-mediated sensitization to TRAIL in glioblastoma cells." (PMID 17376236, 2007). "To place xaf1 in a therapeutic context, we evaluated the role of xaf1 expression in susceptibility to TRAIL-induced apoptosis in glioblastoma cells SF539." (PMID 17376236, 2007). "Stable XAF1 glioblastoma knock-down cell lines were established to characterize the direct implication of XAF1 in IFN-β-mediated sensitization to TRAIL-induced cell death." (PMID 17376236, 2007). "Here, glioblastoma cells SF539 that display relatively high levels of xaf1 transcript, XAF1 protein and very low levels of promoter methylation were assessed for their susceptibility to TRAIL-induced apoptosis before and after shRNA-mediated xaf1 silencing." (PMID 17376236, 2007). "Nevertheless, some evidence shows the over‐expression of XAF1 promotes Temozolomide resistance in GBM cell lines and is negatively correlated with long‐term survival in glioblastoma patients." (PMID 35810383, 2022). "XAF1 knockdown abrogated the temozolomide (TMZ)-induced G2-arrest and prevented TMZ-induced apoptosis in the glioblastoma (GB) cell line LN229." (PMID 28122345, 2017). "In this report, we investigate the effect of IFN-β on the methylation status of xaf1 promoter and on the expression of xaf1 in SF539 and SF295 glioblastoma, SK-N-AS neuroblastoma and HeLa cervical carcinoma." (PMID 17376236, 2007). "Likewise, substantially higher levels of TRIM28 were observed in XAF1−/− versus XAF1+/+ sublines of HT1376 (bladder) and T98G (glioblastoma) cells." (PMID 39532800, 2024). "Of these, glioblastoma SF295 cells have previously been shown to carry little or no detectable XAF1 protein." (PMID 17376236, 2007).
gastric adenocarcinoma (7 papers, 2009 to 2024). "A clinical impact of the XAF1 expression was already shown in epithelial ovarian cancer, pancreatic tumors, clear-cell renal cell cancer, and gastric adenocarcinomas." (PMID 28122345, 2017). "XAF1 was an apoptotic gene whose reduced or absent expression in tumor samples and cell lines leads to poorer survival in gastric adenocarcinomas." (PMID 34367154, 2021). "That the finely tuned balance between XIAP and its antagonists is critical in determining the clinical outcome in cancer patients was demonstrated in an analysis of 187 gastric adenocarcinomas in which the expression levels of XIAP and its antagonising factors including SMAC and XAF1 were examined." (PMID 20485285, 2010). "Moreover, in gastric adenocarcinomas, the expression ratio between XIAP and XAF1 increases and the expression balance of XIAP and XAF1 is an independent prognostic factor." (PMID 19397802, 2009).
glioma (7 papers, 2017 to 2025). A benign or malignant brain and spinal cord tumor that arises from glial cells (astrocytes, oligodendrocytes, ependymal cells). "All of them, except XAF1, are constitutively overexpressed in tumors, including gliomas, and are known to be directly associated with the processes of proliferation and migration of tumor cells." (PMID 41304780, 2025). "Overexpression of miR-873 by using miR-873 mimic markedly decreased XAF1 expression and glioma cells apoptosis caused by WZY-321." (PMID 35517406, 2022). "Taken together, these data indicate that WZY-321 triggers glioma cell apoptosis via XAF1 up-regulation caused by MTM-mediated miR-873 down-regulation." (PMID 35517406, 2022). "Our current studies showed that WZY-321 increased X-linked inhibitor of apoptosis-associated factor 1 (XAF1) expression in glioma cells, and up-regulated XAF1 resulted in glioma cell apoptosis." (PMID 35517406, 2022). "It was noted that promoter hypermethylation of XAF1 was associated with a better prognosis and clinical outcome in high grade gliomas compared to XAF1 promoter hypomethylation." (PMID 31575897, 2019). "Before considering XAF1-targeted MS-HRM as surrogate detection method for IDH mutations in gliomas, this association would have to be proven in a larger cohort." (PMID 28122345, 2017). "The coincidence of XAF1-M and IDH1mut in grade III gliomas explains why this subgroup shows a better survival despite opposite results (for the loss of XAF1) obtained in other tumor types." (PMID 28122345, 2017). "The high association between IDH1 and XAF1 status was also observed in recurrent gliomas." (PMID 28122345, 2017). "Thus, XAF1 methylation status represents a prognostic marker for grade III gliomas, being positively linked to PFS (r = 0.562, p < 0.01) and OS (r = 0.525, p < 0.01)." (PMID 28122345, 2017). "Our current studies showed that miR-873 bound to XAF1 3' UTR and decreased XAF1 mRNA levels in glioma cells." (PMID 35517406, 2022). "Together, these data indicate that XAF1 up-regulation not only contributes to the glioma cell apoptosis but also enhances the sensitivity of glioma cells to anti-tumor drugs." (PMID 35517406, 2022). "Our current studies showed that WZY-321 increased XAF1 expression in glioma cells, and up-regulated XAF1 resulted in glioma cell apoptosis." (PMID 35517406, 2022). "To explore the candidacy of XAF1 as a suppressor in glioma pathogenesis, we initially examined the expression status of XAF1 in cell lines and tissues." (PMID 35274103, 2022). "So, the regulatory effect of WZY-321 on miR-873 expression and miR-873-mediated XAF1 expression in glioma cells and its mechanism need further studies." (PMID 35517406, 2022). "This study uncovers an important role for the XAF1–ATM–AMPK axis as a linchpin to govern glioma response to TMZ therapy." (PMID 35274103, 2022). "The levels of XAF1 expression were determined in the cultured glioma cells after WZY-321 stimulation." (PMID 35517406, 2022). "The data demonstrate that XAF1 promoter methylation determined by MS-HRM is a robust and precise indicator of IDH1 mutations in grade III gliomas." (PMID 28122345, 2017). "Applying this threshold to the glioma cell line panel, a significantly higher XAF1 mRNA expression was found in the unmethylated group (p < 0.0001)." (PMID 28122345, 2017). "WZY-321 could up-regulate XAF1 gene expression and further increase glioma cell apoptosis via decreasing miR-873 expression." (PMID 35517406, 2022). "In contrast, overexpression of MTM could decrease miR-873 expression, and induce XAF1 expression as well as glioma cell apoptosis." (PMID 35517406, 2022). "However, the expression of XAF1 gene in glioma cells after WZY-321 treatment and its roles in WZY-321-induced glioma cell apoptosis are unclear." (PMID 35517406, 2022).